MIR6089 (microRNA 6089 )
Synonyms: MIR6089-1; MIR6089-2; hsa-mir-6089-1; hsa-mir-6089-2
Gene: MicroRNA gene on chromosome X (2,609,191 to 2,609,254, forward strand). Ensembl gene ENSG00000277120.
Diseases named in the same sentence as MIR6089 in open-access papers:
MIR6089 is named in the same sentence as 1 disease in open-access papers, as found by Europe PMC text mining. Sharing a sentence is not in itself a finding about the gene and the disease. The quoted sentences say what the papers report.
cancer (1 paper, 2016). A tumor composed of atypical neoplastic, often pleomorphic cells that invade other tissues. "Most of these genes have not been previously reported in HCC, and BTBD17, MIR6089, ZNF205-AS1 and ZP1 have not previously been linked to cancer; only two genes (DAB2IP and ZNF185) have been reported in HCC." (PMID 27768594, 2016).